GAGE12F (G antigen 12F)
Synonyms: GAGE-12F; OTTHUMG00000024147
Tractability: Antibody: the Human Protein Atlas places it where antibodies can reach.
Gene: Protein-coding gene on chromosome X (49,551,278 to 49,568,218, forward strand). Ensembl gene ENSG00000236362.
Subcellular location (Human Protein Atlas): Plasma membrane; Cytosol; Golgi apparatus
Gene Ontology:
Molecular function: protein binding
Homologues: Orthologues: chimpanzee GAGE10 (82% identical). Paralogues in human: GAGE12G (100% identical), GAGE12C (99% identical), GAGE12D (99% identical), GAGE12E (99% identical), GAGE1 (98% identical), GAGE12H (98% identical), GAGE12J (98% identical), GAGE13 (98% identical), GAGE2A (97% identical), GAGE2E (94% identical), GAGE10 (91% identical), PAGE1 (52% identical), and 10 more.
Diseases named in the same sentence as GAGE12F in open-access papers:
GAGE12F is named in the same sentence as 1 disease in open-access papers, as found by Europe PMC text mining. Sharing a sentence is not in itself a finding about the gene and the disease. The quoted sentences say what the papers report.
COVID-19 (1 paper, 2022). A disease caused by infection with severe acute respiratory syndrome coronavirus 2. "We speculate that the high expression of these immune-related genes can alleviate the aggravation of COVID-19 symptom severity, such as GAGE12F, TNMD, MAGEA6, MAGED2, and XAGE1A." (PMID 36118230, 2022).